EGFR (epidermal growth factor receptor)
Diseases named in the same sentence as EGFR in open-access papers (continued):
Sharing a sentence is not in itself a finding about the gene and the disease.
ovarian carcinoma (continued). "The epidermal growth factor (EGF) receptor (EGFR) is upregulated in ovarian cancer, and increased expression is associated with reduced survival rate." (PMID 25261977, 2014). "Overexpression of EGFR and its downstream targets are associated with resistance to chemotherapy for ovarian cancer." (PMID 25148538, 2014). "For example, in brain, lung, testicular, or ovarian cancers, expression of the EGFR gene, which encodes the epidermal growth factor receptor (EGFR), is greatly upregulated." (PMID 25158017, 2014). "While in some studies, EGFR mutation deletion variant type III was reported in 92% of the ovarian cancers at the FIGO clinical stage III, in other investigations this mutation was not revealed at all." (PMID 24587967, 2013). "Some studies showed that gefitinib can cause complete and long-lasting inhibition of EGFR phosphorylation, which depends on sequestration of inactive drug–receptor complexes in breast and ovarian carcinomas." (PMID 23748900, 2013). "It is interesting to note that BRCA1-mutated ovarian cancer showed dramatically increased expression of EGFR compared with the remaining three groups." (PMID 24321281, 2013). "These limited reports indicate that ovarian cancer progression is closely associated with chemokine networks driven by inflammation or EGFR activation." (PMID 23800251, 2013). "We found that selected ovarian cancer cells were susceptible to cetuximab and anti-EGFR-TKI-treatment, while the majority of cell lines were resistant to single or combination treatment with both substances." (PMID 23109896, 2012). "The expression of both GPR30 and EGFR is associated with a poor outcome in ovarian cancer, and GPR30 increases the phosphorylation of Akt via the EGFR in ovarian cancer cells." (PMID 23163984, 2012). "Since EGFR-overexpression is associated with poor prognosis and is detectable in up to 70% of ovarian cancers targeting the EGF-receptor seemed to be promising." (PMID 23036052, 2012). "The EGFR is reported to be present in 33-75% of ovarian cancers and has been implicated in both the growth and progression of this disease." (PMID 23163984, 2012). "EGFR is not only associated with poor prognosis in ovarian cancer it also promotes alternative splicing of Caspase-9 in favor of Caspase-9b." (PMID 22860069, 2012). "Meanwhile, ovarian carcinoma cells have been found to overexpress epidermal growth factor receptor (EGFR), and EGFR overexpression has been associated with pure clinical outcomes." (PMID 23691448, 2012). "We herein demonstrated that the co-expression of GPR30 and EGFR was associated with a poorer progression free survival in ovarian cancer patients, and that GPR30 activates the phosphorylation of Akt via the EGFR in ovarian cancer cells." (PMID 23163984, 2012). "Due to the association of CRM1 and EGFR protein expression in ovarian carcinomas, we aimed to evaluate the interaction of both in a cell culture model." (PMID 21756326, 2011). "EGFR upregulation is detected in ~60% ovarian cancer and associated with increased tumor cell proliferation, advanced tumor grades and poor patient prognosis." (PMID 21962244, 2011). "Epidermal growth factor receptor (EGFR) is amplified in approximately 4%-22% of ovarian cancer and activating EGFR mutations is rare with a frequency of 4% or less." (PMID 21962244, 2011). "In ovarian cancer, EGFR activation is associated with increased malignant tumor phenotype and poorer patient outcome." (PMID 20037743, 2010). "Activating EGFR mutations, as determined by sequence analyses of potential activating mutation sites in the catalytic domain, is rare in ovarian cancer, with a frequency of 4% or less." (PMID 20037743, 2010). "EGFR is amplified, overexpressed or activated through mutation in many types of human cancers including ovarian cancer." (PMID 20074357, 2010).
ovarian carcinoma (continued). "This is leading to widespread testing of RAS mutations in patients (such as the recent study in ovarian cancer) and, indeed, is approved by the European Medicines Agency as an exclusion criterion for anti-EGFR therapy in colorectal cancer in Europe." (PMID 20037743, 2010). "Further, there is evidence that HER3, a family member also present in ovarian cancers and associated with increased tumor aggressiveness and poor prognosis, plays a critical role in EGFR- and HER2-driven tumors." (PMID 20037743, 2010). "As of late KRAS mutations in ovarian cancer should stand in the center of attention again due to the availability of EGFR-targeted therapies (e.g. Gefitinib, Erlotinib, and Cetuximab), that are already in use to treat patients with NSCLC and metastatic CRC." (PMID 19358724, 2009). "Overexpression of EGFR is found in up to 75% of ovarian cancers and is associated with chemoresistance and poor prognosis." (PMID 18211683, 2008). "Additionally, TKIs targeting EGFR, such as erlotinib and gefitinib, are being evaluated in clinical trials for ovarian cancer, showing potential therapeutic efficacy particularly in ovarian cancer subtypes with EGFR overexpression or mutations." (PMID 40395324, 2025). "EGFR overexpression is associated with poor prognosis in ovarian cancer." (PMID 39858026, 2025). "A possible explanation for this observation is that the inhibitory effects of some EGFR downstream effectors caused by the silencing of MICALL2 may be counteracted by compensatory effects in ovarian cancer cells." (PMID 38203692, 2023). "For instance, in ovarian cancer, the administration of IL-6 neutralizing antibodies causes EGFR upregulation, while the combination of IL-6 neutralizing antibodies with Gefitinib, an EGFR inhibitor, promotes relevant anticancer activity." (PMID 36639824, 2023). "EGFR is upregulated in 35~70% of epithelial ovarian cancers and the enhanced EGFR signaling pathway has been closely linked with the development of an invasive phenotype in various ovarian cancer cell types." (PMID 36768961, 2023). "However, miR‐31 has been associated with resistance to EGFR‐targeted therapies, whereas miR‐382 is a known oncosuppressor in pancreatic and ovarian cancers." (PMID 34921525, 2022). "Both GPER and EGFR overexpression is associated with poor outcome for ovarian cancer." (PMID 36558071, 2022). "In addition, we examined the effect of fentanyl on EGFR-mediated signaling and its association with μ-opioid receptor in ovarian cancer." (PMID 35999506, 2022). "Importantly, PI3K is activated by overexpression of receptor tyrosine kinases including VEGF and EGFR, both of which tend to be upregulated in patients with malignant ascites associated with advanced-stage ovarian cancer." (PMID 34503128, 2021). "EGFR may be used as a promising therapeutic target and EGFR mutations are associated with a poor prognosis in patients with ovarian cancer." (PMID 33281971, 2021). "A study demonstrated that the feedback activation of STAT3 might be the mechanism underlying EGFR inhibitor resistance in ovarian cancer." (PMID 34369236, 2021). "In addition, upregulation of hypoxia and EGFR is also associated with cisplatin resistance in ovarian cancer models, which further supports this possibility." (PMID 32806648, 2020). "Considering the key role of k-ras mutation in EGFR signaling pathway, detecting of k-ras mutations in ovarian carcinoma should stand in the center of attention again, owing to the role of k-ras mutation as a predictive biomarker in poor response to anti-EGFR monoclonal antibody therapies." (PMID 32042390, 2020). "C-X-C motif chemokine ligand 1 (CXCL1) defects may facilitate inflammation and transactivate EGFR in ovarian cancer, but the precise haplotypes associated with the potential diseases remained largely unknown." (PMID 32326946, 2020).
ovarian carcinoma (continued). "High EGFR expression in ovarian cancer is associated with increased proliferation and invasiveness and may be a negative prognostic indicator of survival." (PMID 32231055, 2020). "Numerous studies are still underway to understand the mechanisms underlying TRAIL resistance in ovarian cancer, including combination therapy with cytotoxic chemotherapy, retinoids, proteasome inhibitors, demethylating agents, Akt inhibitors, and EGFR inhibitors." (PMID 32143328, 2020). "Finally, epidermal growth factor receptor (EGFR) is commonly overexpressed in ovarian cancer and associated with poor prognosis." (PMID 30646939, 2019). "We examined whether ovarian cancer cells pretreated with anti-EGFR TKIs (“sensitization”) could regain susceptibility to anti-EGFR antibodies." (PMID 31546690, 2019). "Interestingly, TGFα is implicated in the growth and invasion of ovarian cancer cells via the activation of EGFR signaling." (PMID 30034618, 2018). "Also, the EGFR signaling pathway was overexpressed and associated with poor prognosis in more than 70% of ovarian cancer patients." (PMID 28423672, 2017). "Overexpressed EGFR is associated with poor prognosis in ovarian cancers." (PMID 28423672, 2017). "One possible reason may be shorter CAG repeat alleles promote aggressive ovarian cancer phenotype through variation of epidermal growth factor receptor signaling." (PMID 27741511, 2017). "In addition, epidermal growth factor receptor (EGFR) is overexpressed in human ovarian cancer and is associated with more aggressive clinical behavior and a poor prognosis." (PMID 27835572, 2016). "Deregulation of the EGFR signaling has been found to be associated with the development of a variety of human malignancies including lung, breast, and ovarian cancers, making inhibition of EGFR the most promising molecular targeted therapy developed in the past decade against cancer." (PMID 26580964, 2015). "Interestingly, EGFR mutations have rarely been reported thus far in ovarian cancer, but the receptor expression is readily detectable." (PMID 26639992, 2015). "Both AG1478 and Erotinib are quinazolines, inhibit the EGFR by binding the ATP site thereby preventing autophosphorylation of the receptor and have been linked to reversal of drug resistance or modulation of drug resistance in ovarian cancer." (PMID 26351843, 2015). "As these EGFR signaling pathways have been extensively linked to proliferation in ovarian cancer, activation of these pathways by SPINK1 offers a plausible mechanism by which SPINK1 may exert its proliferative effects in cell culture." (PMID 26437224, 2015). "In addition, the overexpression of BRCA1 can effectively reduce the expression of EGFR in BRCA1-mutated ovarian cancer cells." (PMID 24321281, 2013). "Evidence obtained from overexpression and knockdown analyses indicates a critical role for HE4 in ovarian cancer cell adhesion, migration and progression, which may be associated with activation of the EGFR-MAPK signaling pathway." (PMID 23894390, 2013). "Further, aberrant EGFR expression is associated with poor outcome of ovarian cancer patients." (PMID 20037743, 2010). "Moreover, EFEMP2 could bind to EGFR to induce PD-L1 regulation in ovarian cancer, which was caused by the activation of EGFR/ERK1/2/c-Jun signaling." (PMID 37420173, 2023). "Moreover, the EGFR or ERBB2 overexpression could cause resistance to ovarian cancer cell death and increase tumor-initiating capacity." (PMID 35889396, 2022). "We found that CAFs from malignant fluids of ovarian cancer receive a specific signaling pattern from cancer cells, mainly composed of ligands associated with neovascularization processes, differentiation pathway, EGFR tyrosine kinase inhibitor resistance, and IL-6/JAK/STAT3 signaling." (PMID 36352420, 2022).
ovarian carcinoma (continued). "Dysregulation of EGFR-mediated signaling may lead to alterations in signaling pathways involved in cell cycle regulation, angiogenesis, and metastasis and is associated with a malignant phenotype for ovarian cancer." (PMID 34503128, 2021). "Notably, high α2,3-sialyltransferase type I (ST3Gal I) expression is associated with advanced stage epithelial ovarian cancer and has been linked to ovarian cancer cell migration and peritoneal dissemination via an epidermal growth factor receptor-dependent mechanism." (PMID 29594046, 2018). "However, it still remains to be determined if activation by EGF or somatic-activating mutations in the kinase domain of EGFR has any effect on the production of IL-6 or GP130 family of cytokines that can lead to the activated status of STAT3 in ovarian carcinomas." (PMID 19088723, 2009). "In this study, we developed four ADCs targeting epidermal growth factor receptor (EGFR), epidermal growth factor receptor 2 (Her2), trophoblast cell-surface antigen 2 (Trop2), and tissue factor (TF) that are highly expressed on ovarian cancer cells." (PMID 41908461, 2026). "Intravenously injected nimotuzumab-conjugated NK92 ACDVs decreased the tumour volumes of EGFR-expressing ovarian cancer xenografts in mice." (PMID 41618610, 2026). "Quantitative analysis showed significant downregulation of FOXP3 and EGFR mRNA expression in SKOV3 ovarian cancer cells after 48 h of treatment with Hes, ADR, and their combination (Hes + ADR) at IC50 concentrations." (PMID 41301890, 2025). "RT-qPCR and protein expression results showed that TQ and Dox can provide active treatment in ovarian cancer via the EGFR and FOXP3 signaling pathways." (PMID 40172364, 2025). "Synergistic effects were observed in vitro when free melittin was combined with cisplatin in resistant ovarian cancer cells, as well as with EGFR inhibitors in NSCLC cells." (PMID 40871040, 2025). "The drug combination between RAPTA-C and the epidermal growth factor receptor (EGFR) inhibitor, erlotinib, resulted in strong synergistic inhibition of cell viability in human endothelial and human ovarian carcinoma cells." (PMID 41155174, 2025). "In this study, we used scFv-SNAP-tag, targeting ovarian cancer cells expressing EGFR, Her2, FOLR1, TROP2, and TF antigen to generate 1:1 antibody IR700 ratio, which is important to get robust pharmacokinetic, efficacy, and safety profiles." (PMID 41362788, 2025). "For example, genomic biomarkers such as EGFR and BRCA1/2 mutations guide targeted therapies like EGFR inhibitors (erlotinib, gefitinib) for NSCLC and PARP inhibitors (olaparib, niraparib) for BRCA1/2‐mutated breast and ovarian cancers." (PMID 40636286, 2025). "In one study, it was proven that bufalin can bind to EGFR via the molecular docking method and thus suppress the proliferation of ovarian cancer cells." (PMID 40172364, 2025). "Our results provide new mechanistic insights regarding the regulation of EGFR by SORL1 in ovarian cancer." (PMID 39858026, 2025). "Although other oncogenic and tumor-suppressive genes were predicted in silico, FOXP3 and EGFR were prioritized for their dual mechanistic relevance and translational potential as therapeutic markers in ovarian cancer." (PMID 41301890, 2025). "Another important focus is developing integrated safety switches, such as the EGFR safety switch in ovarian cancer MUC16 CAR-T." (PMID 40969260, 2025). "In cisplatin-resistant ovarian cancer cells, m7G modification significantly enhances translation of EGFR pathway genes and activates PI3K/AKT/mTOR signaling, which reduces apoptosis sensitivity." (PMID 40895564, 2025). "We were able to suppress the proliferation of ovarian cancer cells with TQ by carrying out molecular regulation that targeted EGFR." (PMID 40172364, 2025). "Later, the same group examined the synergistic effects of targeting the PAFR and EGFR signaling on the antitumor efficacy of ovarian cancer." (PMID 40160442, 2025).
ovarian carcinoma (continued). "In this study, we developed five NIR-PIT agents by conjugating scFv-SNAP-tag fusion proteins with BG-modified IRdye700 to target ovarian cancer cells, which expressed cell surface antigens epidermal growth factor receptor (EGFR), Her2, FOLR1, TROP2, and TF." (PMID 41362788, 2025). "GALNT14 has emerged as a key regulator of both ferroptosis and apoptosis in ovarian cancer through its effects on epidermal growth factor receptor (EGFR) glycosylation and downstream mTOR pathway activation." (PMID 41008983, 2025). "EGFR amplification or its high expression in ovarian cancer plays an important role in the prognosis of the disease." (PMID 40172364, 2025). "In ovarian cancer (OC), both EGFR- and VEGF-A-mediated signaling pathways are often upregulated and cooperate to promote tumor growth and angiogenesis." (PMID 40969763, 2025). "EGFR is not only abnormally expressed in cervical cancer, but also overexpressed in ovarian cancer, and downregulation of EGFR expression inhibits ovarian cancer cell proliferation." (PMID 40309242, 2025). "CA-125, also known as mucin 16, is a large surface glycoprotein, known to be involved in the modulation of epidermal growth factor receptor (EGFR) phosphorylation, and is commonly used for the diagnosis and management of ovarian cancer." (PMID 40075577, 2025). "For lung and ovary cancers, all three selected drug pairs were combinations of an EGFR inhibitor and an HDAC inhibitor." (PMID 41230525, 2025). "AREG is a secreted glycoprotein and low-affinity epidermal growth factor receptor (EGFR) ligand and has an established role in promoting ovarian cell proliferation, metastasis, cancer stemness, and therapy resistance in ovarian cancer." (PMID 38831884, 2024). "For the initial assessment of antitumoral NK cell activity in ovarian cancer, we implemented an in vitro coculture system consisting of healthy donor NK cells, EGFR-positive tumor cells, and the anti-EGFR antibody Cetuximab that mediates ADCC." (PMID 38646521, 2024). "These experiments show that Casc4 regulates ovarian cancer cell survival, dissemination, and EGFR protein levels in vivo." (PMID 38030811, 2024). "Xiang-Yang Zeng, Xiao-Yan Jiang, Jia-Hui Yong, Hui Xie, Jing Yuan, Da Zeng, Ying-Yu Dou, Song-Shu Xiao "lncRNA ABHD11-AS1, regulated by the EGFR pathway, contributes to the ovarian cancer tumorigenesis by epigenetically suppressing TIMP2" Cancer Med." (PMID 38470371, 2024). "Specifically, ST6GAL1 can mediate resistance to chemoradiation in rectal cancer, the sensitivity of gastric cancer cells to trastuzumab, and resistance to the EGFR inhibitor, gefitinib, in ovarian cancer." (PMID 39272811, 2024). "This suggests a plausible relationship between EGFR and OVCAR4 cells, implicating EGFR signaling in ovarian cancer progression and therapy resistance." (PMID 39194519, 2024). "As mentioned already, EGFR is a promising target for PIT due to frequent overexpression in ovarian cancers." (PMID 39261715, 2024). "To assess this, we used the syngeneic ID8 murine ovarian cancer cell line model (an EGFR-competent cell line), which is considered an orthotopic model insofar as it recapitulates the tendency of human HGSC to target the omentum as a primary dissemination site." (PMID 38030811, 2024). "In summary, we have identified the Golgi-localized protein CASC4 as a driver of anoikis resistance in ovarian cancer through regulation of EGFR trafficking." (PMID 38030811, 2024). "These outcomes indicate that VM can suppress the migratory and invasive properties of ovarian cancer cells by modulating the EGFR/Ras/MEK/ERK signaling pathway." (PMID 38372808, 2024). "FGFR3 overexpression enhances the cisplatin resistance in ovarian cancer through elevating the phosphorylation of the epidermal growth factor receptor (EGFR) and further activating the PI3K/AKT signaling pathway." (PMID 38542707, 2024).